MMP9 (matrix metallopeptidase 9)
Diseases named in the same sentence as MMP9 in open-access papers (continued):
Sharing a sentence is not in itself a finding about the gene and the disease.
tumor (continued). "The MMP-9 cleaved TRZ-hFc4 and TRZ-Fc4 exhibited EC50 values and maximal tumor cell lysis similar to Trastuzumab." (PMID 34413859, 2021). "MMP-9 plays a prominent role in angiogenesis by cooperating with VEGF, and it is produced by metastatic tumor cells and metastasis-infiltrating neutrophils and/or macrophages." (PMID 34830300, 2021). "CHI3L1 can promote tumor progression by upregulation of pro‐inflammatory mediators, like CCL2, CXCL2, and MMP‐9." (PMID 33626234, 2021). "MMP-9 can also activate TGF-ß in a functional complex with CD44 on the surface of keratinocytes and selected tumor cells." (PMID 33807594, 2021). "Western blot assay demonstrated that the downregulation of ALKBH5 reduced the expression of the tumor metastasis-related proteins matrix metallopeptidase 2 (MMP2), MMP7, and MMP9 in UM cells." (PMID 33428593, 2021). "We first tested cleavage kinetics of several reported MMP substrates, and selected one (PLGVRGK) with optimized MMP9 specificity using FRET-based fluorometric peptide substrate cleavage assays with purified MMP9 enzyme and lysates from tumor tissue samples." (PMID 34267368, 2021). "In the lycopene treatment group, there was reduction in tumor load, Ki67, ITGA5 ITGA5B1, ascites CA125 but there was an increment in MMP-9." (PMID 34202203, 2021). "PMs were first subjected to different formulations and then activated to secrete the tumor-supportive cytokines (i.e., VEGF-B, PDGF-α, and MMP-9)." (PMID 33536421, 2021). "Matrix metalloproteinase 9 (MMP-9), an endopeptidase, can degrade the extracellular matrix and basement membrane and plays a key role in tumor invasion and metastasis." (PMID 33828938, 2021). "Microglia secretes a variety of mediators that promote tumor growth and invasion, such as MMPs, MMP-2 and MMP-9, who are considered to be the key enzymes involved in glioma invasion." (PMID 34284780, 2021). "However, serum MMP-9 showed results that could not be considered beneficial for the diagnosis of advanced neoplasia in the CRC family-risk population screening." (PMID 34502094, 2021). "The diagnostic sensitivity of TIMP-1 was higher (61%) than that of the serum levels of other biomarkers (MMP-9—55%; TIMP-2—59%, MMP-2—46%) as well as the classical tumor markers (CEA and CA 19-9), and increased in combined use with CEA." (PMID 34071492, 2021). "Neutrophils can release neutrophil elastase, matrix metalloprotease 8 (MMP8), matrix metalloprotease 9 (MMP9), vascular endothelial growth factor (VEGF), cathepsin G and proteinase-3 to degrade the extracellular matrix (ECM) and promote tumor invasion." (PMID 33526991, 2021). "Pro-tumor N2 neutrophils induce progression of the disease and release of CXCL1, MMP9, VEGF, and TNF-alpha." (PMID 35008550, 2021). "Given the fact that PPARγ has been reported to act as a tumor suppressor in several cancers and PPARγ silencing increased the expression of C-myc, NF-κB, CyclinD1, cyclin E, MMP2, and MMP9 in BC cells." (PMID 33777130, 2021). "A novel inhibitor of TLR-2, ortho vanillin, inhibited MMP-9, MMP-14, IL-6, and iNOS expression and decreased TLR-2-mediated pro-tumor M2 phenotype of brain resident macrophages." (PMID 34439380, 2021). "As we found the reduced mRNA levels of matrix metalloproteinase (MMP) 2 and MMP9 in tumor tissues from LNCaP xenografts injected with GV1001, we further assessed both mRNA and protein expressions of MMP2 and MMP9 in LNCaP cells exposed to vehicle or GV1001." (PMID 34743733, 2021). "MMP-9 seems to play a major role in tumor angiogenesis, and when overexpressed in HCC, a higher tumor progression is noted due to increased lymph node invasion, promotion of metastasis, deficient differentiation, and overall poor prognosis." (PMID 34835933, 2021). "Then, we checked the expression of these proteins in the subcutaneous tumor tissues and found that high CEACAM6 expression can also promote the expression of p-Src, p-PI3K, p-Akt, and MMP9 proteins in vivo." (PMID 34221964, 2021).
tumor (continued). "MMP-2 and MMP-9 are members of the matrix metalloproteinase family that can decompose ECM and induce tumor metastasis." (PMID 34612136, 2021). "The subsequent uptake of soluble heparanase by tumor cells initiated ERK and Akt signaling pathways, stimulated the expression of vascular endothelial growth factor (VEGF), HGF, and MMP-9, and was correlated with an aggressive tumor phenotype." (PMID 33800172, 2021). "EGR1 can synergistically act with SNAIL on the promoter regions of MMP9 and ZEB1, thereby enhancing their transcription and initiating tumor cell invasion and metastasis." (PMID 33842351, 2021). "Especially, CS reduced the tumor area and nodules that spread to lung and liver by suppressing MMP-2 and MMP-9." (PMID 33801741, 2021). "Treatment with other FQs, such as clinafloxacin and gatifloxacin, also reduced TGF-β-stimulated MMP-9 production, which implied that most FQs share the common ability to suppress MMP-9 production and tumor metastasis." (PMID 34769032, 2021). "Consistently, the protein levels of TRIM44, p-STAT3, BCL2, MMP9, HIF-1α and PIM1 were all decreased in SPATS2 knockdown tumor tissues, which underpinned the contribution of SPATS2-TRIM44-p-STAT3 axis to tumorigenic events in HCC." (PMID 33391405, 2021). "Ginsenoside Rg3, the main active component of Shenyi capsule, inhibits tumor migration by inhibiting proto-oncogene (C-Myc), cyclooxygenase-2 (COX-2), and matrix metalloproteinase-9 (MMP-9)." (PMID 34512772, 2021). "Exosomes containing MALAT1 are released into the tumor microenvironment, inhibiting and depleting YAP1, activating ERK1/2 signal transduction, and enhancing the expression of MMP2 and MMP9, thereby promoting tumor invasion and metastasis." (PMID 35145971, 2021). "Western blot result uncovered that Ki67, PCNA, MMP-2, and MMP-9 were notably repressed upon ADAMTS9-AS1 overexpression (p < 0.05), indicating that the tumor proliferation was decreased." (PMID 34900984, 2021). "Western blot result uncovered that Ki67, MMP-9, MMP-2, PCNA and other tumor markers were prominently activated after the downregulation of ADAMTS9-AS1, indicating increased tumor proliferative activity." (PMID 34900984, 2021). "SiRNA-mediated knockdown of PKM2 resulted in an upregulation of tumor suppressors, including Bad, caspase 7, and E-cadherin, whereas oncogenes, such as MMP-2, MMP-9, HIF1α, and VEGF, were downregulated in the SK-OV-3 cells." (PMID 34131394, 2021). "Then, to identify the role of BMDCs in the invasion of OSCC, we examined the expression of MMP9 and MMP2 in the invasion front line of tumor specimens by performing IHC staining." (PMID 35008304, 2021). "MMP9 was upregulated in LK0902 and LK0917 tumor cells/CAFs spheroids, but in LK1108, only a few cells were positively stained for MMP9." (PMID 34283070, 2021). "Neutrophils secrete proangiogenic cytokines, which include IL-8, MMP-9, MMP-8, and VEGF, which are known to contribute to tumor angiogenesis and progression." (PMID 34446028, 2021). "Consistently, the expression levels of M2-related tumor-supportive factors, VEGF-B, PDGF-α, and MMP-9, were determined to be significantly downregulated after RG@M-γ-CD treatment." (PMID 33536421, 2021). "M2 TAMS drive tumor cell EMT via GM-CSF and CCL18 while N2 TANs remodel the ECM of tumor cells via Neutrophil Elastase (NE) and MMP9." (PMID 34830776, 2021). "It has been reported that high levels of matrix metalloproteinases, such as MMP-1, MMP-2, MMP-9, and MMP-14, produced by tumor cells participate in VM37." (PMID 33850110, 2021). "Our study also determined the tumor-suppressing function of SNHG1 knockdown at molecular levels, corresponding to reductions in MMP-2, MMP-9, Bcl-2, and N-cadherin and elevations in Bax and E-cadherin." (PMID 34095464, 2021).
tumor (continued). "Ginsenoside Rg3 can decrease the expression of MMP-2, MMP-9 and VEGF in B16 cell tumor mouse model and in vitro B16 cell model." (PMID 34746014, 2021). "GSEA was performed to discover potential molecular mechanisms of MMP9 and IGFBP1 in tumor immune and progression." (PMID 33758602, 2021). "MDSCs interact with the TME, and tumor and stromal cells secrete TGF-β, MMP9, BV8, IL-6, IL-1β, β-FGF and VEFG through autocrine and paracrine mechanisms, mobilizing and expanding MDSCs and further promoting tumor growth." (PMID 34925375, 2021). "Matrix metalloproteinase-9 (MMP-9), one of the most representative matrix metalloproteinases, promotes tumour invasion and metastasis by degrading the extracellular matrix." (PMID 33632232, 2021). "The pro-tumor microenvironment of GBM is supported by the expression of MMPs by TAM, including MMP-2 and MMP-9, which are involved in tumor growth by having an impact on angiogenesis, apoptosis and cell proliferation." (PMID 32765498, 2020). "In comparison to a wild-type fiber adenovirus, AdTATMMP demonstrated increased infection of tumor cells as well as patient-derived CAFs that highly expressed MMP2 and MMP9." (PMID 33167307, 2020). "These embryonic bridging macrophages secrete numerous genes shared by the perivascular macrophages that drive tumor angiogenesis including the angiopoietin receptor, Tek, the VEGF co-receptor Nrp1, growth factors (Fgf2, Pgf) and MMPs (Mmp2, Mmp9)." (PMID 32484158, 2020). "MMPs (MMP-2, MMP-3, MMP-7, MMP-9, MMP-13, and MT1-MMP) degrade the ECM, which then facilitates the extravasation of tumor cells and CSC." (PMID 32974184, 2020). "To further investigate the concentrations of MMP-9 and IGF-1 within the tumor microenvironment, we also analyzed the tumor tissue 17 days after Plasmodium infection." (PMID 32972437, 2020). "We performed H&E staining to verify tumor tissues and immunohistochemistry to detect the expression of OTUD7B, TRAF3, NIK, Ki67, MMP9 and IL-2 in the xenografted tissues." (PMID 33198776, 2020). "26, 27 Moreover, a PC in vivo experiment suggested that salidroside suppressed tumor growth, increased cell apoptosis, inhibited the metastasis of BxPC‐3 cells to the lung, and reduced HIF‐1α, LOXL2, MMP2, and MMP9 while enhanced E‐cadherin in tumor tissue." (PMID 31162697, 2020). "MMP9, VEGF, and vimentin are involved in promoting tumor metastasis, while E-cadherin is involved in its suppression." (PMID 32667904, 2020). "About MMP-9, HIV-protease inhibitors including darunavir, lopinavir, saquinavir, and ritonavir directly down-regulate its expression in normal or tumor cells and in treated patients." (PMID 32528888, 2020). "Several MMPs were found to be expressed by the cancer cells (e.g., MMP-7); however, others were synthesized by the tumor stromal cells (e.g., MMP-2, MMP-9)." (PMID 33287452, 2020). "On the other hand, VEGF is the key molecule of angiogenesis, and MMP-9 is the most important member of the MMP family, which involves in tumor metastasis." (PMID 32957430, 2020). "Of note, the activities of MMP-9 and MMP-2, the two major metalloproteinases (MMPs) responsible for ECM remodeling and tumor invasion, were significantly lower in the tumor microenvironment of TNFR1 KO mice." (PMID 33202705, 2020). "NETs releasing neutrophils eventually release PGE2, IL-8, matrix metalloproteinase-9 (MMP9), ELANE and other tumor promoters plausibly accounting for a more invasive growth of neighboring tumor cells." (PMID 32098278, 2020). "Our finding indicated that arctigenin decreased the expression of tumor-derived cytokines, including GM-CSF, MMP-3, MMP-9 and TSLP." (PMID 32887217, 2020). "MMPs have also been established as key players in mechanisms of tumor invasion and metastasis formation by ECM degradation and are regulated by AP-1 and NF-κB, being MMP-9 strongly regulated by the latter." (PMID 32599967, 2020).
tumor (continued). "MMPs, such as MMP-2 and MMP-9, are produced as inactive forms (pro-MMP) that need to be activated by cleavage to promote tumor cell migration." (PMID 32268584, 2020). "This pathway can also regulate the expression of MMP‐2 and MMP‐9, which not only degrades the ECM, enhances the aggressiveness of tumor cells, but also maintains the microenvironment of tumor growth." (PMID 32786144, 2020). "The activation of MMP-9 mediated by OPN induces ECM degradation, cell invasion, tumor growth and metastasis." (PMID 32392801, 2020). "Expression levels of MMP-2 and MMP-9, major metalloproteinase proteins, produced by GBM cells during tumor invasion was observed following ATX incubation for 24 h by immunoblotting and gelatin zymography, respectively." (PMID 32711429, 2020). "In another study, we showed that chemotherapy induces upregulation of MMP-9 specifically in BMDCs, an effect which facilitates EMT in tumor cells and supports their dissemination from the primary tumor site." (PMID 33276524, 2020). "Thus, MMP-9/NGAL complex may contribute to tumor progression and metastasis." (PMID 32856853, 2020). "Myoepithelial cells can act on tumor cells and on fibroblasts to reduce MMP-2, MMP-9, and MT1-MMP gene expression, decreasing cancer cells invasive capacities." (PMID 32984031, 2020). "MMP-9 degrades the extracellular matrix (ECM) via proteolysis, which in turn promotes the migration and invasion of tumor cells." (PMID 32708058, 2020). "When a tumor first becomes vascularized (angiogenic switch), MMP-2 and MMP-9 have been shown to be critical for tumor angiogenesis." (PMID 33096744, 2020). "The protein levels of VEGF, MMP9, MMP2 and LOX increased in the sera of CT26‐P2X7R tumour‐bearing mice compared with those of CT26‐Con mice." (PMID 32735377, 2020). "MMP-2, MMP-7, MMP-9, and MMP-12 belong to metalloproteinases (MMPs), a family of zinc-binding enzymes related to tumor invasion and angiogenesis." (PMID 33113766, 2020). "CD147 not only plays a role in lactic acid transportation, but it also can stimulate tumor cells to produce MMPs, specifically MMP-2 and MMP-9, which further promotes tumor invasion and metastasis." (PMID 33178600, 2020). "Secretion of MMP-2 and MMP-9 activate the latent form of transforming growth factor-beta (TGF-β), further promoting tumor invasion and angiogenesis." (PMID 31690961, 2020). "Within the TME, M2-like TAMs promote cancer cell proliferation through the activation of the MMP9/HB-EGF pathway and epidermal growth factor (EGF) production, leading to the stimulation of VEGF signaling that supports tumor metastasis." (PMID 32354198, 2020). "Several studies have reported CLIC1 to be an overexpressed protein in CRC, involved in cell migration and invasion, including more tumor recurrences and shorter patient survival, through the regulation of MMP-2 and MMP-9." (PMID 32353950, 2020). "Overexpression of CSE also increased the levels of MMP2 and MMP9 in early metastatic breast cancer cells, allowing the degradation of the ECM and consequently the entering of tumor cells into the blood circulation." (PMID 32085654, 2020). "The inhibitory effect of XYS was accompanied by downregulated expression of TGF-β, IL-6, MMP-9 and VEGF in spleen tumours, as well as suppression of VEGF and CD31 proteins in hepatic metastatic tissue." (PMID 33152259, 2020). "MMPs play an important role in tumor invasion and metastasis, and among many MMPs, MMP2 and MMP9 are well characterized in invasiveness and metastasis." (PMID 32029709, 2020). "Consistent with their expression in TAMs, MMP-9 and IGF-1 expression was also significantly decreased in the infected tumor tissue; however, the expression of VEGF was only slightly decreased in the infected tumors compared with the uninfected tumors." (PMID 32972437, 2020).
tumor (continued). "Neutrophils seem to act mostly as promoters of tumor progression as indicated by the induction of EMT and angiogenesis after the secretion and release of matrix metalloproteinase-9 (MMP-9) and elastase." (PMID 32397303, 2020). "Interestingly, we found that knockdown of exosomal circRNA-100,338 could significantly suppress tumor growth, microvessel density, MMP9 expression levels, and reduce the number of lung metastatic nodules and the positive rate of Ki67 in lung metastatic nodules of the nude mice models." (PMID 31973767, 2020). "It has been demonstrated that tumor cells invasion or metastasis are dramatically reduced by COX-2 inhibitors, and this effect is mediated by a significant reduction in PGE2-mediated MMP-9 expression/activity." (PMID 32973660, 2020). "Evidences also suggest that TAMs promote tumor metastasis through producing matrix metallopeptidase (MMP), such as MMP2, MMP7, and MMP9." (PMID 33201893, 2020). "Inflammation occurs in the tumor microenvironment, which in turn accumulates a large number of cytokines, chemical mediators and enzymes, such as TNF-a, IL-6, VEGF, iNOS, Cox-2, and MMP-9, for mediating inflammation and driving its malignant transformation." (PMID 31343435, 2020). "EMT and MMPs are critical for the metastasis of tumour cells; thus, we examined the expression levels of EMT and MMPs markers, such as E-cadherin, vimentin, N-cadherin, MMP2 and MMP9, to explore their correlation with VEGF." (PMID 33193893, 2020). "And CXCR4 positive cells increased expression of MMP9 and MMP15, which are known to play an important role in extracellular matrix remodeling during the process of tumor invasion and metastasis." (PMID 32232002, 2020). "MMP2, MMP9, VEGF, arginase, and elastase from neutrophil degranulation can also contribute to tumor progression." (PMID 33488669, 2020). "LMP1 containing EVs modify the microenvironment by upregulating cadherins, fibronectin, integrin-α5, MMP9 and MMP2 to promote a tumor permissive niche leading tumorigenesis or metastasis." (PMID 33382850, 2020). "It develops in response to tumor-derived factors and releases IL10, IL12, TNFα, TNFβ, VEGF, CCL20, CCL22, and MMP9, thereby supporting tumor growth and metastases and acting as an immunosuppressant." (PMID 32900001, 2020). "Circulating MMP9 is elevated in CRC patients, and in resected primary CRC, tumor MMP9 expression is an independent predictor of disease-free survival." (PMID 32781554, 2020). "MMP2 and MMP9 are gelatinases that are able to degrade and remodel ECM; for these reasons MMP2 and MMP9 play important roles in promoting the metastasis of tumour cells." (PMID 33228670, 2020). "In gastric cancer, this SNHG15 functions as a tumor promoter by up-regulating MMP2 and MMP9, followed by stimulation of proliferation and invasion." (PMID 32318335, 2020). "The expression levels of CD31, MMP-9, and TGF-β1 in the tumor tissues of the mice treated with saline were higher than those in the tumor tissues of the mice treated with S/C-pW-LPNs." (PMID 32473632, 2020). "At the same time, MMP9 plays a key role in the formation, invasion, and metastasis of CRC by promoting neovascularization, capillary proliferation, and tumor cell growth and proliferation." (PMID 33144895, 2020). "The levels of angiogenic growth factor, VEGF, MMP2, and MMP9 secreted into ascites fluid during the growth of EAT cells and tumor cells were reduced in the presence GA or CA as compared to the saline-treated control group mice." (PMID 33261130, 2020). "Further in vitro and in vivo study found that the FOXM1 inhibitor thiostrepton inhibited PTC cell line xenograft tumor growth and this was accompanied by downregulation of FOXM1, MMP9, and MMP2." (PMID 32603365, 2020). "Functionally, EFEMP1 inhibits migration of tumor cells by regulating MMP2 and MMP9 via ERK1/2 activity." (PMID 32555395, 2020).